MYCN (MYCN proto-oncogene, bHLH transcription factor)
Diseases named in the same sentence as MYCN in open-access papers (continued):
Sharing a sentence is not in itself a finding about the gene and the disease.
embryonal tumors (18 papers, 2009 to 2026). "The delineation of the mechanistic underpinnings of MYCN oncogenic activity in pediatric embryonal tumors provides a rationale to target both these cofactors simultaneously, which has important therapeutic implications for patients with MYCN-driven tumors." (PMID 38547242, 2024). "In this review, we focus on the role of lipid metabolism in embryonal neoplasms with MYCN dysregulation." (PMID 37046804, 2023). "In the next few sections, we discuss the various lipid metabolic reactions that were found to be altered in individual embryonal tumors with MYCN dysregulation." (PMID 37046804, 2023). "Here we focus on lipid metabolism and its role in tumor pathogenesis and progression of embryonal tumors with alterations in MYCN comprising NB, RB, MB, RMS, and WT." (PMID 37046804, 2023). "MYCN likewise was found to be deregulated in embryonal tumors." (PMID 37046804, 2023). "Given its correlation with rapid tumor progression and poor prognosis in several embryonal cancers MYCN is considered an ideal therapeutic target, but many direct or indirect MYCN modulators failed to result in an efficient MYCN specific therapy." (PMID 39079981, 2024).
leukemia (17 papers, 2009 to 2025). A malignant (clonal) hematologic disorder, involving hematopoietic stem cells and characterized by the presence of primitive or atypical myeloid or lymphoid cells in the bone marrow and the blood. "Several reports illustrated, driven by specific promoters, that overexpression of MYCN or MYCC in mice or zebrafish causes lymphoma or leukemia." (PMID 23554972, 2013). "The implication of MYCN in the genesis of T-cell leukemias and lymphomas was suggested by few previous studies on the evidence of high MYCN expression in neoplasms arisen in transgenic mice or found in leukemia and lymphoma cell lines." (PMID 24334727, 2014). "Additionally, BI-2536 sensitive SCLC cells statistically exhibited enrichment in c-MYC and MYCN signatures from other cancer types and normal cells, including colorectal, leukemia, lymphoma, blood B cells, and fibroblasts." (PMID 39085197, 2024). "Spearman correlation analyses between UHRF1 mRNA levels and the gene expression of MYC family members (MYC, MYCN, and MYCL1), as well as CDK4 and CDK6 in the Haferlach and Gu leukemia datasets, indicated positive associations between UHRF1 and c-Myc, CDK4, and CDK6 in ALL." (PMID 36077796, 2022). "Notably, several essential genes involved in HSC self-renewal, metabolism, and leukemia development were increased, including GATA2, MSI2, MYCN, CD44, GAS2, HOXB4, and HOXB6." (PMID 38216972, 2024). "In contrast, neither MYC nor its homologue MYCN could initiate leukemia within 200 days under these experimental conditions, indicating that activation of the MYC high signature alone is insufficient for leukemogenesis in vivo." (PMID 34310280, 2021).
melanoma (17 papers, 2009 to 2025). A malignant, usually aggressive tumor composed of atypical, neoplastic melanocytes. "Increased mRNA expression of these T cell transcripts and MYCN in melanomas was associated with improved overall survival." (PMID 36768931, 2023). "Nevertheless, the involvement of MYCN, which is associated with early skin development in mammals and which is expressed in keratinocytes, suggests that GABAergic signaling in melanoma cells may activate an early developmental program in keratinocytes that supports melanoma growth." (PMID 39201498, 2024). "Analysis of mRNA expression data for melanomas in The Cancer Genome Atlas identified a significant coexpression of MYCN with CD47 and known regulators of CD8 T cell function." (PMID 36768931, 2023). "Analysis of TCGA RNAseq data for melanoma cell lines in The Cancer Cell Line Encyclopedia indicated minimal or undetectable MYCN expression in melanoma cells." (PMID 36768931, 2023). "The expression of these genes was also positively correlated with that of MYCN in the melanomas but inversely correlated with that of MYC." (PMID 36768931, 2023). "Underexpression of plexin receptor C1 (PLXNC1), a receptor characterized as a tumor suppressor in melanoma was observed in late stage and MYCN-amplifying NB in seven cases." (PMID 23106811, 2012). "We also considered the alternate hypothesis that the effects of MYCN or MYC expression on survival results from their expression in melanoma cells." (PMID 36768931, 2023). "Determining whether specific isoforms of MYCN play direct roles in the CD47-dependent regulation of other immune regulators in CD8 cells in vitro or in melanomas will require further study." (PMID 36768931, 2023). "In addition, three candidate genes, MYCN, PPP6C, and STK19, known to be associated with melanoma development, might be considered as new BCC driver genes." (PMID 29165358, 2017). "In an ADRN PDX model (MYCN amplified) that developed indisulam resistance, cancer cells lost their ADRN features and were enriched with expression features of melanoma markers such as MITF." (PMID 40962798, 2025). "GABA-A receptor–positive keratinocytes were found to mediate their protumorigenic effect by upregulating MYCN, a known upstream activator of LIF expression, and by secreting LIF, which in turn increases melanoma cell proliferation." (PMID 39201498, 2024). "Taken together, these data suggest that the MYCN mRNA detected in the TCGA melanomas is expressed in CD8 T cells and is another marker of their activation, which would be consistent with the positive correlation between MYCN and overall survival." (PMID 36768931, 2023). "Therefore, the correlation between MYCN and survival probably relates to a function of MYCN in nonmalignant cells in the melanoma microenvironment, but we cannot exclude additional roles for MYCN expressed in stromal cells other than T cells." (PMID 36768931, 2023). "For comparison, in a lysate of the melanoma cell line (BLM), which does not carry MYCN-amplification, no reactivity could be observed." (PMID 19615087, 2009).
osteosarcoma (17 papers, 2014 to 2025). A usually aggressive malignant bone-forming mesenchymal neoplasm, predominantly affecting adolescents and young adults. "Wnt/beta-catenin signaling showed very strong inverse correlation with ICR in Osteosarcoma but not in high risk NBL without MYCN amplification." (PMID 35690832, 2022). "Direct co-regulation has been observed between TUBB, RPLPO and ACTB via v-myc myelocytomatosis viral (MYCN) and between TUBB and RPLPO via FBJ murine osteosarcoma viral (FOS)." (PMID 25881111, 2015). "Expression analysis might give further insights whether c-MYC, MYCN, and/or other oncogenes orchestrate together in H3F3A G34 mutant osteosarcomas." (PMID 28484590, 2017). "We performed a per-cancer analysis of the 5 pediatric solid tumor types present in the TARGET cohort and found that the disposition of an immune active phenotype characterized by ICR high was associated with favorable prognosis in Osteosarcoma and high risk NBL without MYCN amplification." (PMID 35690832, 2022). "Since ICR was most prognostic in Osteosarcoma and high risk NBL without MYCN amplification, we proceeded to examine which tumor intrinsic attributes correlate with immune infiltration, reflected by ICR score, in OS and high risk NBL without MYCN amplification." (PMID 35690832, 2022). "Experiments supported E2F-Sp1 interactions near: dihydrofolate reductase in Chinese hamster, dihydrofolate reductase in human osteosarcoma, fibroblast CTP:phosphocholine cytidylyltransferase in mouse embryo, thymidine kinase in mouse, RIP140 in human, CDKN2A, HMGA1, MYCN, and CDKN2C." (PMID 27871221, 2016).
ganglioneuroblastoma (16 papers, 1997 to 2024). A neuroblastic tumor characterized by the presence of neuroblastic cells, ganglion cells, and a stroma with Schwannian differentiation constituting more than fifty-percent of the tumor volume. "The survival difference does not reach statistically significant in only three subgroups (MYCN‐amplified subgroup, differentiating subgroup and ganglioneuroblastoma subgroup) with low case number." (PMID 32683778, 2020). "Non-MYCN-amplification was observed in the contemporaneous 77 ganglioneuroblastomas and 55 ganglioneuromas in our center." (PMID 30245940, 2018). "But copy number analyses of MYCN gene in ganglioneuroblastoma (GNBL) and ganglioneuroma(GN) is poorly described in the literature." (PMID 23320395, 2013). "Based on the INRGSS, very low-risk tumors encompass stage L1/L2 maturing ganglioneuroma or intermixed ganglioneuroblastoma, stage L1 tumors with non-amplified MYCN, and stage MS in children younger than 18 months of age with no 11q aberration." (PMID 37835497, 2023).
lymphoma (16 papers, 2013 to 2024). A malignant (clonal) proliferation of B- lymphocytes or T- lymphocytes which involves the lymph nodes, bone marrow and/or extranodal sites. "Over-expression of specific MYC family genes is frequently associated with particular types of human tumors; MYCN deregulation is almost exclusively associated with solid tumors and only rarely observed in lymphomas." (PMID 26453442, 2015). "Although MYCN is more commonly deregulated in human solid tumors (especially for childhood onset), it has also been reported translocated in human lymphomas, mouse plasma cell tumors, and, importantly, expressed in the very few human BL cases apparently lacking MYC deregulation." (PMID 33816589, 2021). "Transgenic mice overexpressing MYCN and MYCC Via the Eμ enhancer (targeted to B cell) develop lymphoma after a latency period of 2 to 5 months." (PMID 23554972, 2013).
astrocytoma (15 papers, 2012 to 2025). "Finally, the focal amplifications included as part of this analysis represent a subset of prognostically significant amplifications described for IDH1/2-mutant astrocytomas, such as MYCN." (PMID 39584448, 2025). "Variations of BCOR, MYCN, NOTCH1, and PIK3R1 and positive immunohistochemistry for S100 showed statistically significant results in univariate survival analysis in WHO grade 4 astrocytoma." (PMID 38970209, 2024). "MYCN, a member of MYC proto-oncogenes, expression levels may have a positive relationship with disease-free survival in astrocytoma and meningioma." (PMID 32122297, 2020).
liver cancer (14 papers, 2015 to 2025). An epithelial or non-epithelial malignant neoplasm that arises from the liver. "The absorbance at 450 nm in the sgMYCN groups was visibly lower than that in the control groups on Day 5, revealing that knockout of MYCN exerted a significant inhibitory effect on the proliferative capacity of liver cancer cells." (PMID 39248163, 2024). "To investigate the effect of MYCN expression on the growth of liver cancer cell lines, we designed sgRNAs targeting the exons of MYCN, and verified the function of MYCN in the Huh7‐Cas9 and MHCC97L‐Cas9 cell lines." (PMID 39248163, 2024). "In conclusion, these results demonstrated that HSF1 occupies both the promoter and SE regions of MYCN, thus activating its transcription in liver cancer cells." (PMID 39248163, 2024). "Taken together these results indicated that HSF1 promoted the proliferation of liver cancer cells by regulating MYCN." (PMID 39248163, 2024). "The results indicated that in conjunction with the downregulation of HSF1, MYCN expression was also downregulated, suggesting that MYCN is a downstream target of HSF1 in liver cancer cells." (PMID 39248163, 2024). "In HCC, multiple studies have demonstrated that inhibiting MYCN expression can reduce the proliferation and invasion of liver cancer cells." (PMID 39248163, 2024). "The mRNA and protein level of MYCN was significantly decreased in both liver cancer cell lines after infection with lentiviruses containing the sgRNAs." (PMID 39248163, 2024). "The results indicated that HSF1 functions as a transcription factor and directly binds to the promoter and SE of MYCN in liver cancer cells." (PMID 39248163, 2024). "Mechanistically, our findings demonstrate that HSF1 transcriptionally activates MYCN expression by binding to its promoter and SE elements, thereby promoting liver cancer cell proliferation." (PMID 39248163, 2024). "Some authors have discussed the role of RA action in the prevention and treatment of MYCN-positive liver cancer stem cells, and it is apparent that a profound alteration of retinoid signaling is a crucial characteristic of Peruvian HCC." (PMID 33747361, 2021). "Therefore, understanding and tracing the dynamic changes and functions of MYCN gene expression will shed light on the origin of liver tumorigenesis at the cellular level and the development of novel therapeutic and diagnostic strategies for liver cancer treatment." (PMID 33937011, 2020). "Taken together, these data strongly suggest the tumor-suppressive role of miR-142-5p through post-transcriptional control of MYCN and its therapeutic potential in liver cancer." (PMID 33937011, 2020). "More recently, our group highlighted MYCN as another major target of miR-493-5p using global gene expression analysis of liver cancer cells with restored expression of miR-493-5p." (PMID 33937011, 2020). "Moreover, their findings demonstrated that HSF1 is bound to its promoter and SE elements to transcriptionally activate MYCN expression, thereby promoting liver cancer cell proliferation." (PMID 40606603, 2025). "In order to investigate whether HSF1 promotes the proliferation of liver cancer cells by regulating MYCN, we designed and conducted a rescue experiment in Huh7 and MHCC97L cell lines." (PMID 39248163, 2024). "However, little is known about the miRNAs involved in the posttranscriptional regulation of MYCN in liver cancer." (PMID 33937011, 2020). "Upregulated MYCN gene expression is restricted to specialized cell populations such as EpCAM+ cancer stem cells in liver cancer, regardless of DNA amplification and mutation." (PMID 33937011, 2020). "MYCN gene is overexpressed in restricted cell populations such as EpCAM+ CSCs in liver cancer, regardless of DNA amplification and mutation." (PMID 33937011, 2020). "Additionally, knockdown of MYCN reduced the colony forming ability of liver cancer cell lines." (PMID 39248163, 2024).
liver cancer (continued). "To explore how HSF1 regulates MYCN expression in liver cancer cells, we further investigated the regulatory mechanism of HSF1 on MYCN at the transcriptional level." (PMID 39248163, 2024). "This highlights the existence of non-genomic mechanisms potentially responsible for MYCN overexpression in liver cancer." (PMID 33937011, 2020). "Notably, data mining in TCGA showed that the expression of MYCN in human HCC was not correlated with that of c-MYC, another MYC family membranes known to be crucial for liver cancer maintenance and oncogenic reprogramming of terminally differentiated hepatocytes into liver cancer stem cells (CSCs)." (PMID 33937011, 2020).
neuroendocrine tumors (14 papers, 2016 to 2026). "Several AURKA inhibitors have demonstrated anti-proliferative efficacy in preclinical models of neuroendocrine tumors by disrupting the MYCN-AURKA complex." (PMID 38016952, 2023). "Previous studies have reported that MYCN, an oncogenic regulator involved in multiple neuroendocrine tumors, undergoes amplification and is overexpressed in 40% of NEPC cases, compared with only 5% incidence in prostate adenocarcinoma cases." (PMID 38016952, 2023). "It was illustrated that only neuroendocrine tumor cells gained MYCN copies instead of all cells in the NB microenvironment in previous single-cell analyses." (PMID 35493068, 2022). "We characterize the MYCN induced neuroendocrine tumors in mice and provide insights into their biology." (PMID 27769070, 2016). "In summary, we provide a novel mouse model for neuroendocrine tumors of the pancreas and pituitary gland that is dependent on MYCN expression and that may help to evaluate MYCN-directed therapies." (PMID 27769070, 2016). "Thus, we here not only describe a novel transgenic model for neuroendocrine tumors, but also provide a framework for the evaluation of new, MYCN-directed therapies." (PMID 27769070, 2016). "Sustained ectopic MYCN expression may suffice to induce oncogenic transformation in this setting, whereas MDM2-mediated positive feedback, to further upregulate MYCN translation, is needed for development of intrinsically MYCN-driven neural and neuroendocrine tumors." (PMID 33425720, 2020). "The results obtained by MYCN silencing by BGA002 in SCLC were also similarly found when treating NB, another highly aggressive and MYCN-related neuroendocrine tumor." (PMID 36765949, 2023).
triple-negative breast carcinoma (13 papers, 2016 to 2025). An invasive breast carcinoma which is negative for expression of estrogen receptor (ER), progesterone receptor (PR), and human epidermal growth factor receptor 2 (HER2). "Given that MYCN plays significant roles in various cancer types, including triple-negative breast cancer, we sought to determine its importance in normal mammary gland development." (PMID 40862719, 2025). "Combined BET and MEK inhibition resulted in a synergistic decrease in tumor viability in MYCN-expressing triple-negative breast cancer." (PMID 35487914, 2022). "It was reported that the triple-negative breast cancer (TNBC) cell lines with higher expression level of MYCN are more sensitive to BET inhibitor." (PMID 36187481, 2022). "Moreover, the MYCN expression status could affect the sensitivity of triple-negative breast cancer (TNBC) cells to JQ1 and the cells with lower MYCN expression were less sensitive to JQ1." (PMID 37543638, 2023).
pancreatic cancer (12 papers, 2013 to 2025). "In pancreatic cancer, decreased levelsof PCNA were linked with alterations in the NRF2 pathway, while alterationsin the MYC/MYCN and HIPPO pathways was linked with increased PCNAlevels in lung and pancreatic cancer." (PMID 40657100, 2025).
acute lymphoblastic leukemia (10 papers, 2014 to 2025). Leukemia with an acute onset, characterized by the presence of lymphoblasts in the bone marrow and the peripheral blood. "Both chronic lymphocytic leukemia (CLL) and acute lymphoblastic leukemia (ALL) have been associated with MYCN-amplification." (PMID 28358317, 2017). "Previous studies have revealed the role of miR-19/CYLD/NFKB and miR-429/MYCN/MFHAS1 FFLs in the development or relapse of T-lineage acute lymphoblastic leukemia (T-ALL)." (PMID 35805200, 2022). "MYCN has been demonstrated to have lower methylation levels in relapsed children with B-cell acute lymphoblastic leukemia (B-ALL), which was consistent with the usage of MYCN in this study as a key feature to differentiate B-ALL." (PMID 36033519, 2022). "Here we show that MYCN is overexpressed in a relevant proportion (40 to 50%) of adult and pediatric T-cell acute lymphoblastic leukemias (T-ALL)." (PMID 24334727, 2014).
Ewing sarcoma (10 papers, 2017 to 2025). A small round cell tumor that lacks morphologic, immunohistochemical, and electron microscopic evidence of neuroectodermal differentiation. "Examples include MYCN amplifications driven by extrachromosomal DNA in NB and EWSR1::FLI1 fusions caused by chromoplexy in Ewing sarcoma." (PMID 41228232, 2025).
alveolar rhabdomyosarcoma (9 papers, 2018 to 2025). A rapidly growing malignant mesenchymal neoplasm. "For example, in alveolar rhabdomyosarcoma (aRMS), the fusion oncogene PAX3::FOXO1 (or PAX7::FOXO1) binds SEs together with other MTFs, including MYOD, MYOG, and MYCN, to sustain proliferation, and their depletion leads to altered proliferation and cell death." (PMID 41444391, 2025).